SASS6 (SAS-6 centriolar assembly protein)
Description:
Central scaffolding component of the centrioles ensuring their 9-fold symmetry (By similarity). Required for centrosome biogenesis and duplication: required both for mother-centriole-dependent centriole duplication and deuterosome-dependent centriole amplification in multiciliated cells. Not required for centriole formation in embryonic stem cells but necessary to maintain centriole architecture (By similarity). Required for the recruitment of STIL to the procentriole and for STIL-mediated centriole amplification. Overexpression results in excess foci-bearing centriolar markers.
Synonyms: SAS6; DKFZp761A078; SAS-6; FLJ22097; MCPH14
Tractability: Small molecule: a structure with a bound ligand is known. PROTAC: UniProt records ubiquitination sites on it; ubiquitination databases record sites on it.
Gene: Protein-coding gene on chromosome 1 (100,083,563 to 100,132,955, reverse strand). Ensembl gene ENSG00000156876.
Subcellular location: Cytoplasm, cytoskeleton, microtubule organizing center, centrosome; Cytoplasm, cytoskeleton, microtubule organizing center, centrosome, centriole
Subcellular location (Human Protein Atlas): Cytosol; Primary cilium; Vesicles
Gene Ontology:
Molecular function: protein binding
Biological process: centriole replication; centrosome duplication; positive regulation of centriole replication; positive regulation of G1/S transition of mitotic cell cycle; positive regulation of spindle assembly; regulation of mitotic spindle organization; spermatogenesis
Cellular component: centriole; centrosome; cytoplasm; procentriole replication complex; deuterosome
Genetic constraint (gnomAD): Loss-of-function variants: 5 observed, 8.74 expected, observed/expected ratio (o/e) 0.57, 90% interval 0.3 to 1.2. That is too few expected variants to judge how well the gene tolerates losing a copy. Missense variants: 90 observed, 103.34 expected, observed/expected ratio (o/e) 0.87, 90% interval 0.73 to 1.04. Synonymous variants: 33 observed, 37.24 expected, observed/expected ratio (o/e) 0.89, 90% interval 0.67 to 1.18.
Homologues: Orthologues: chimpanzee SASS6 (100% identical), macaque SASS6 (98% identical), rabbit SASS6 (92% identical), dog SASS6 (91% identical), pig SASS6 (91% identical), mouse Sass6 (85% identical), rat Sass6 (84% identical), guinea pig SASS6 (79% identical), zebrafish sass6 (55% identical), tropical clawed frog sass6.2 (48% identical).
Diseases named in the same sentence as SASS6 in open-access papers:
SASS6 is named in the same sentence as 19 diseases in open-access papers, as found by Europe PMC text mining. Sharing a sentence is not in itself a finding about the gene and the disease. The quoted sentences say what the papers report.
lung carcinoma (3 papers, 2019 to 2025). "Consistent with previous research, we found that SASS6 expression was associated with poor prognosis in a number of tumors, including lung cancer." (PMID 40825584, 2025). "Interestingly, analysis of The Cancer Genome Atlas (TCGA) showed that high levels of SASS6 expression were consistent with poor prognosis in adrenocortical carcinoma, low-grade glioma, and kidney, liver, and lung cancer patients." (PMID 40825584, 2025).
Primary microcephaly (3 papers, 2018 to 2025). Head circumference below 2 standard deviations below the mean for age and gender at birth. "Since the gene’s initial association with autosomal recessive (AR) primary microcephaly in 2014, seven causative SASS6 variants (all missense or putative splice variants) have been reported in seven individuals across four families." (PMID 40597352, 2025). "A novel SASS6 variant, p.(Glu412Gly), was identified in both partners of a couple who had 2 pregnancies with primary microcephaly (case 14)." (PMID 29096039, 2018).
microcephaly (2 papers, 2021 to 2025). A congenital or acquired developmental disorder in which the circumference of the head is smaller than normal for the person's age and sex. "A positive role of SAS-6 in cilium formation is supported by work in Caenorhabditis elegans showing that a microcephaly-associated SASS6 mutation results in shorter phasmid cilia." (PMID 40825584, 2025). "The CmC analysis revealed that selective pressure on different parts of phylogeny is not significantly divergent for all analyzed microcephaly loci except for SASS6 in the comparison of simians and nonsimians placental mammals." (PMID 33941077, 2021).
ovarian carcinoma (1 paper, 2017). A malignant neoplasm originating from the surface ovarian epithelium. "Ovarian cancer cells were more sensitive to the depletion of STIL than to other centriolar replication factors including PLK4, SASS6 and CENPJ." (PMID 28423708, 2017).
paraplegia (1 paper, 2023). Complete paralysis of the lower half of the body including both legs, often caused by damage to the spinal cord. "FYCO1 also has interaction potential with CCZ1B involved in vacuolar transport, ZFYVE27 (the spastic paraplegia gene), CXCR6, and SASS6 involved in centriole duplication." (PMID 37629644, 2023).
cancer (5 papers, 2020 to 2025). A tumor composed of atypical neoplastic, often pleomorphic cells that invade other tissues. "Particularly, SASS6 overexpression was found to correlate with poor prognosis in a number of tumor types, highlighting the relevance of SAS-6 in cancer progression." (PMID 40825584, 2025).
SASS6 also shares sentences with these, for which no sentence is quoted: infection (3 papers); autosomal recessive primary microcephaly (2); breast carcinoma (2); malaria (2); abortion (1); adrenocortical carcinoma (1); cyst (1); glioma (1); hepatocellular carcinoma (1); lung adenocarcinoma (1); metastatic disease (1); renal papillary cell carcinoma (1); tumor (1).